SNRNP200 (small nuclear ribonucleoprotein U5 subunit 200)
Diseases named in the same sentence as SNRNP200 in open-access papers:
SNRNP200 is named in the same sentence as 31 diseases in open-access papers, as found by Europe PMC text mining. Sharing a sentence is not in itself a finding about the gene and the disease. The quoted sentences say what the papers report.
retinitis pigmentosa (14 papers, 2013 to 2025). Retinitis pigmentosa (RP) is an inherited retinal dystrophy leading to progressive loss of the photoreceptors and retinal pigment epithelium and resulting in blindness usually after several decades. "Mutations in PRPF8 and SNRNP200 are found in patients with retinitis pigmentosa (RP), a human hereditary disease characterized by the loss of photoreceptors and degenerative changes in the retinal pigment epithelium (RPE)." (PMID 40045025, 2025). "Variants in TXNL4A and EFTUD2 manifest in craniofacial malformations while variants in PRPF8 and SNRNP200 manifest in retinitis pigmentosa." (PMID 40264708, 2025). "Another spliceosomal gene, SNRNP200, which mutations cause retinitis pigmentosa, was also prominently expressed in cartilages in addition to the retina." (PMID 36058892, 2023). "Mutations in genes encoding the splicing factors PRPF3, PRPF8, PRPF31, RP9, and SNRNP200 can cause non-syndromic retinitis pigmentosa, a severe form of inherited blindness leading to rod photoreceptor degeneration." (PMID 26985665, 2016). "Elucidating the pathogenesis for SNRNP200 mutations would aid in the development of novel therapeutics for retinitis pigmentosa." (PMID 26137319, 2015). "Mutations in six spliceosomal proteins, PRPF3, PRPF4, PRPF6, PRPF8, PRPF31 and SNRNP200, cause retinitis pigmentosa (RP), a disease characterized by progressive photoreceptor degeneration." (PMID 25383878, 2014). "Mutations in SNRNP200/BRR2, a Ski2-like RNA helicase that appears to be a key component of the U5 SNRNP complex, are associated with retinitis pigmentosa, a form of degenerative blindness." (PMID 38329136, 2024). "The small nuclear ribonucleoprotein 200 kDa (SNRNP200) gene plays a key role in the maturation of pre-message RNA (pre-mRNA) splicing with the indication for the etiology of retinitis pigmentosa (RP)." (PMID 33553197, 2020). "Particularly melanoma, carcinoma and solid tumors have the most significant enrichment of these genes, including ABCC11 (melanoma drug resistance), SNRNP200 (retinitis pigmentosa), TRERF1 (breast cancer) and WTX (Wilms tumor gene on X chromosome, Wilms tumor)." (PMID 25523808, 2014). "Small nuclear ribonucleoprotein U5 200kDa subunit (SNRNP200), on the other hand, has been linked to retinitis pigmentosa (RP, MIM: 610359), which does not feature craniofacial anomalies." (PMID 41427026, 2025). "Retinitis pigmentosa is a genetic disorder of the eyes characterized by a loss of vision and is sometimes caused by mutations in specific spliceosomal proteins, such as PRPF8 and SNRNP200." (PMID 36560714, 2022).
autosomal dominant retinitis pigmentosa (8 papers, 2012 to 2024). Autosomal dominant retinitis pigmentosa (RP) is an autosomally dominant inherited retinal dystrophy leading to progressive loss of the photoreceptors and retinal pigment epithelium and resulting in blindness usually after several decades. "SNRNP200, a key component of the RNA splicing machinery, was found to be essential for proper cell cycle progression and possibly linked to autosomal dominant retinitis pigmentosa." (PMID 39199615, 2024). "At least six different proteins of the spliceosome, including PRPF3, PRPF4, PRPF6, PRPF8, PRPF31, and SNRNP200, are mutated in autosomal dominant retinitis pigmentosa (adRP)." (PMID 30967900, 2019). "Six mutations in SNRNP200 have recently been discovered to be associated with autosomal dominant retinitis pigmentosa (adRP)." (PMID 23029027, 2012). "In addition to mutations that affect the splicing of specific retinal genes, mutations in genes associated with ubiquitously core snRNP proteins, such as PRPF3, PRPF4, PRPF6, PRPF8, PRPF31, SNRNP200/BRR2 and splicing factors such as RP9 and DHX38 lead to autosomal dominant retinitis pigmentosa." (PMID 31740647, 2017).
viral infection (6 papers, 2016 to 2025). "In this study, we systemically deciphered the impact of the viral μ2 protein from MRV on transcripts encoding the U5 snRNP proteins EFTUD2, PRPF8, and SNRNP200, in an effort to understand how μ2 triggers a reduction in the level of their corresponding proteins during viral infection." (PMID 36614170, 2022). "For example, cytoplasmic EFTUD2 and SNRNP200 act as RNA sensors that induce interferon production during viral infection." (PMID 40580566, 2025). "In this study, we demonstrated distinct and overlapping crucial roles of U5 snRNP core components EFTUD2, PRPF8, and SNRNP200 on apoptosis, necroptosis, and interferon induction during viral infection, using MRV as a model virus." (PMID 36560714, 2022). "Upon viral infection, SNRNP200 binds vRNA through its amino-terminal Sec 63 (Sec63-1) domain, relocates to the perinuclear region, and acts as an adaptor protein to potentiate IRF3 signaling." (PMID 29854853, 2018). "Upon viral infection, a subcellular fraction of SNRNP200 relocalizes with TBK1 into perinuclear cytoplasmic speckles." (PMID 27454487, 2016). "Mechanistically, it was found that, upon viral infection, SNRNP200 relocates to some undefined cytoplasmic structures were it is able to directly sense viral RNA." (PMID 27454487, 2016). "Indeed, both EFTUD2 and SNRNP200 have been shown to act as RNA sensors in the cytoplasm to allow the induction of the IFN response pathway during viral infection." (PMID 35489070, 2022). "In summary, it has been demonstrated that upon virus infection, the SNRNP200 RNA helicase in combination with TBK1 via its Sec63-1 domain recognizes viral RNA, relocalizes into TBK1-containing cytoplasmic structures, and positively regulates IRF3 phosphorylation to promote the antiviral response." (PMID 27454487, 2016). "Much like other DExD/H box RNA helicases, SNRNP200 requires a functional ATPase/helicase activity in addition to a competent Sec63-1 domain of unknown function to promote IRF3-dependent IFN induction upon virus infection." (PMID 29854853, 2018). "We demonstrated that EFTUD2 and SNRNP200 are required for both apoptosis and necroptosis, whereas EFTUD2 and PRPF8 are required for optimal interferon response against viral infection." (PMID 36560714, 2022). "The results presented herein highlight novel roles of U5 snRNP proteins EFTUD2, PRPF8, and SNRNP200 in apoptosis, necroptosis, and interferon induction, using MRV as a model for viral infection." (PMID 36560714, 2022). "For instance, we demonstrated that EFTUD2 and SNRNP200 are required for both apoptosis and necroptosis, whereas EFTUD2 and PRPF8 are required for optimal interferon response against viral infection." (PMID 36560714, 2022). "The regulatory role of SNRNP200 is confirmed in the MDM and PBMCs of RP33 patients due to the impaired production of IFN-β upon viral infection." (PMID 27454487, 2016). "In the present study, we deciphered the impact of EFTUD2, PRPF8, and SNRNP200 silencing on viral replication using MRV as a model and discovered novel roles for EFTUD2 and SNRNP200 in cell survival, apoptosis, and necroptosis during viral infection." (PMID 36560714, 2022). "The results suggest that SNRNP200 specifically regulates IRF3 activation upon RNA virus infection to promote IFNB1 induction and IFN effector responses, and thus demonstrates its importance in controlling viral infections." (PMID 27454487, 2016).
retinal degeneration (4 papers, 2018 to 2025). Degeneration of the retina. "For example, why variants in the U5 snRNP genes PRPF6, PRPF8 and SNRNP200 are associated with retinal degeneration in adRP, while variants in the U5 snRNP genes EFTUD2 and TXNL4A are linked to craniofacial disorders, is not understood." (PMID 31304552, 2019). "The knocking down of endogenous SNRNP200 in zebrafish using MO has been previously demonstrated to cause retinal degeneration, indicating that an insufficient gene quantity of SNRNP200 could result in RP in patients." (PMID 33553197, 2020).
breast carcinoma (3 papers, 2014 to 2024). "In MPS2 breast cancer cells, there was a consistent and significant increase in the expression of these crucial proteins, with SNRNP200 exhibiting the most pronounced fluctuations in response to glucose concentrations." (PMID 39285160, 2024).
prostate carcinoma (2 papers, 2024). A carcinoma that arises from epithelial cells of the prostate gland. "The role of the spliceosome, particularly the U5 snRNP’s 200 kDa helicase encoded by the SNRNP200 gene, is also crucial, given its association with tumor aggressiveness in prostate cancer." (PMID 39199615, 2024). "Furthermore, SNRNP200 is implicated in the aggressiveness of prostate cancer tumors, highlighting its role in tumor pathology and suggesting its potential as a target for therapeutic intervention." (PMID 39199615, 2024). "The overexpression of SNRNP200 in prostate cancer has been associated with tumor aggressiveness." (PMID 39199615, 2024).
Atrophy (1 paper, 2022). Any weakening or degeneration, especially through lack of use. "Due to the progressive muscle atrophy of the affected individuals, we additionally investigated if the aggregates contained SNRNP200, another CAPRIN1 interacting partner that has been reported in the cortical and spinal motor neurons of ALS cases and indeed we could detect it." (PMID 36136249, 2022).
Blindness (1 paper, 2025). Blindness is the condition of lacking visual perception defined as a profound reduction in visual perception. "Mutations in PRPF8 and SNRNP200 as well as several other splicing factors cause retinal cell degeneration, leading to vision impairment and eventually to blindness." (PMID 40045025, 2025).
clear cell renal cell carcinoma (1 paper, 2024). "This study explored the protein expression levels of UCHL1, SNRNP200, and PAK4 in clear cell renal cell carcinoma (CCRCC) using advanced proteomic techniques." (PMID 39199615, 2024).
COVID-19 (1 paper, 2022). A disease caused by infection with severe acute respiratory syndrome coronavirus 2. "Our results showed that six spliceosomal component proteins (DDX5, DDX17, DDX39B, PRPF6, SNRNP40, and SNRNP200) were significantly down-regulated in COVID-19 patients." (PMID 35421082, 2022). "Specifically, two small nuclear ribonucleoprotein U5 subunits (SNRNP40 and SNRNP200) and multiple splicing factors (e.g., HNRNP A0, A2B1, A3, DL, F, H1, H2, L, LL, R, U, UL1, UL2 and SRSF6) were significantly under-expressed in the COVID-19 patients." (PMID 35421082, 2022).
ovarian carcinoma (1 paper, 2021). A malignant neoplasm originating from the surface ovarian epithelium. "Secondly, we identified more accurate and reliable hub genes including EIF3M, RPS27A, SNRNP200 and UBR4, and we also performed an enrichment analysis to characterize the role of AS in ovarian cancer." (PMID 34001978, 2021). "In this paper, we identified the potential gene with prognosis-related AS event in ovarian carcinomas (the multiple genes presented in the network), and EIF3M, RPS27A, SNRNP200 and UBR4 were found at the core of gene interaction network." (PMID 34001978, 2021).
retinal dystrophies (1 paper, 2016). "RP is a rare inherited disease of retinal dystrophies with an incidence of one in 3,000–4,000, of which 1.6% bear mutations in the SNRNP200 gene." (PMID 27454487, 2016).
cancer (7 papers, 2014 to 2024). A tumor composed of atypical neoplastic, often pleomorphic cells that invade other tissues. "We found that UCHL1 and SNRNP200 are significantly upregulated, and PAK4 is downregulated in high-grade CCRCC, and all are involved in critical cellular pathways linked to cancer progression and poor clinical outcomes." (PMID 39199615, 2024). "Current therapeutic approaches for targeting SNRNP200 in CCRCC are still emerging but there is significant potential based on findings from studies in other cancers, particularly AML." (PMID 39199615, 2024). "Conversely, SNRNP200 knockdown in MCF10A cells resulted in minimal growth reduction, highlighting the selective vulnerability of glycolytic cancer cells to SNRNP200 depletion." (PMID 39285160, 2024). "One can postulate that RP-associated variants and cancer-linked somatic mutations affect different aspects of PRPF8 function, although RP PRPF8 variants can affect both spliceosome assembly and SNRNP200 regulation (Ru°žičková and Staněk, 2017)." (PMID 33584830, 2021). "By revealing the intricate connections among SNRNP200-mediated splicing dynamics, metabolite-driven PTMs, and metabolic profiles in TNBC subtypes, we provide new insights into cancer biology and therapeutic opportunities." (PMID 39285160, 2024). "SNRNP200 is a U5 small nuclear ribonucleoprotein 200 kDa helicase that promotes metabolic reprogramming and abnormal metabolism in TNBC cancer cells by enhancing glycolysis and glutathione metabolism." (PMID 39795985, 2024). "This suggests that UCHL1, SNRNP200, and PAK4 could serve as valuable prognostic markers, offering new insights into the progression and prognosis of this aggressive cancer subtype." (PMID 39199615, 2024).
infection (6 papers, 2016 to 2023). The state of being infected such as from the introduction of a foreign agent such as serum, vaccine, antigenic substance or organism. "Knockdown of two proteins (EFTUD2 and SNRNP200) belonging to the U5 snRNP family resulted in a reduction of p-MLKL after infection of L929 cells with reovirus T3DS (reovirus variant derived from the Lemay lab)." (PMID 36768641, 2023). "EFTUD2 and SNRNP200 are thus required for induction of necroptosis during MRV infection while EFTUD2’s importance for necroptosis appears to be generalized to other necroptotic stimuli, such as zVAD-fmk/TNFα." (PMID 36560714, 2022). "The structural protein μ2 appears to be the main determinant of these AS modifications by decreasing the levels of U5 core components EFTUD2, PRPF8, and SNRNP200 during infection." (PMID 36614170, 2022). "We previously demonstrated that MRV reduces the protein levels of EFTUD2, PRPF8, and SNRNP200 through the action of the μ2 protein during infection." (PMID 36560714, 2022). "In contrast, SNRNP200 had limited effect on the cell’s ability to respond to infection through the IFN response pathway, highlighting once again the specific and different roles of these proteins belonging to the same snRNP." (PMID 36560714, 2022). "μ2 impacts cellular AS by interacting with U5 snRNP proteins EFTUD2, PRPF8, and SNRNP200, and reducing their levels during infection." (PMID 36560714, 2022). "Together, these data show that U5 snRNP proteins EFTUD2 and SNRNP200 are involved in cell survival and/or cell death after infection with MRV." (PMID 36560714, 2022). "We show that SNRNP200 relocalizes into TBK1-containing cytoplasmic structures upon infection, in contrast to the RP33-associated S1087L mutant, which is also unable to rescue antiviral response of SNRNP200 knockdown cells." (PMID 27454487, 2016). "Upon infection, SNRNP200 binds viral RNA and relocalizes into TBK1-containing cytoplasmic structures to promote IRF3 activation and IFNB1 production." (PMID 27454487, 2016). "The depletion of SNRNP200 reduced IFN-β production at 8 hours post-infection reaching levels comparable to those obtained in DDX58 KD cells at 48 hours post-infection." (PMID 27454487, 2016). "In contrast to the unchanged TNFα mRNA levels, a decrease in IFNB1 mRNA was observed, which correlates with the reduced SNRNP200 mRNA at 1 hour post-infection in MDM." (PMID 27454487, 2016). "Surprisingly, T3DS infection led to a striking reduction in PRPF8 (80%) protein levels, and a more modest reduction in EFTUD2 (35%) and SNRNP200 (25%)." (PMID 35489070, 2022). "More importantly, the silencing of SNRNP200 in MDM decreases the induction of IFIH1 and IFIT1, and completely blocks IRF3 Ser386 phosphorylation within 3 hours post-infection." (PMID 27454487, 2016). "The P208S mutation did not affect the reduction of either PRPF8 or SNRNP200, suggesting the P208S mutant retains its ability to reduce PRPF8 levels, as seen during T3DK infection." (PMID 35489070, 2022). "We also validated that the depletion of EFTUD2, PRPF8, and SNRNP200 was not decreasing cell viability, and that cell survived and even expanded throughout the course of the experiment in the absence of infection." (PMID 36560714, 2022). "Notably, SOD1 is an important interaction molecule that exists both in BALF, PBMC and serum, and participates in early and late stages of infection, followed by PRKAR1A, IARS, SNRNP200, and DHX15." (PMID 34952961, 2021). "Finally, the silencing of SNRNP200 completely blocks IRF3 Ser386 phosphorylation in MDM, even when IRF3 protein levels are similar to control cells, resulting in the blockage of IFN-β secretion at 3 hours post-infection." (PMID 27454487, 2016). "Unlike WT SNRNP200, the staining of the FLAG-SNRNP200 S1087L mutant shows neither relocalization of the protein nor colocalization with TBK1 into these cytoplasmic speckles upon infection, correlating with its lack of RNA binding." (PMID 27454487, 2016).
tumor (5 papers, 2020 to 2024). "To further examine whether the tumor-promoting function of SNRNP200 relies on its regulation of enzymatic activities and cellular metabolism, we conducted a rescue assay." (PMID 39285160, 2024). "This analysis revealed a noteworthy upregulation in the expression levels of SNRNP200 and downregulation of UCHL1 and PAK4 proteins in the CPTAC tumor samples compared to normal samples." (PMID 39199615, 2024). "Endogenous IP assays confirmed the interaction between SNRNP200 and HDAC5 in MPS2 tumor cells." (PMID 39285160, 2024).
retinal disorder (1 paper, 2016). Any disease or disorder of the retina. "The findings in the PBMC of patients with a monoallelic point mutation in SNRNP200 established a deregulation of innate immunity, which may affect cell viability in different retinal disorders, as these cells and neural cells are usually non-proliferative and long-lived." (PMID 27454487, 2016).
SNRNP200 also shares sentences with these, for which no sentence is quoted: acute myeloid leukemia (2 papers); acrofacial dysostosis (1); amyotrophic lateral sclerosis (1); cerebrocostomandibular syndrome (1); cyst (1); degenerative disease (1); leukemia (1); melanoma (1); Nager syndrome (1); Nonsyndromic Orofacial Cleft (1); retinal disease (1); rheumatoid arthritis (1); Seizure (1); syndromic (1); Wilms tumor (1).